SIRT4 (sirtuin 4)
Diseases named in the same sentence as SIRT4 in open-access papers (continued):
Sharing a sentence is not in itself a finding about the gene and the disease.
prostate carcinoma (12 papers, 2020 to 2025). A carcinoma that arises from epithelial cells of the prostate gland. "In this study, we showed that overexpression of SIRT4 downregulated the proteins associated with migration and invasion and inhibited the proliferation, migration, and invasion capabilities of prostate cancer cells." (PMID 35842463, 2022). "Notably, a significant association of SIRT4 expression levels with Gleason score was also revealed in patients with prostate cancer." (PMID 35842463, 2022). "In conclusion, the present study’s findings showed that SIRT4 protein levels are significantly associated with the Gleason score in patients with prostate cancer, and SIRT4 exerts a tumor-suppressive effect on prostate cancer cells by inhibiting glutamine metabolism." (PMID 35842463, 2022). "SIRT4 inhibits the uptake of glutamine, a metabolite essential for the proliferation of tumor cells, which in turn limits the growth of prostate cancer cell lines." (PMID 41304967, 2025). "SIRT4 stimulates mitochondrial-mediated death in prostate cancer cell lines by deacetylating adenine nucleotide translocase-2, which is highly expressed in the mitochondrial inner membrane in cancers, and triggering its degradation." (PMID 41304967, 2025). "We also detected a positive correlation between SIRT4 and autophagy pathways in other adenocarcinomas, including colon cancer, rectal cancer, prostate cancer, and lung adenocarcinoma." (PMID 36209169, 2023). "In a recent prostate cancer study, overexpression of SIRT4 inhibited the proliferation, migration, and invasive ability of prostate cancer cells and promoted apoptosis of prostate cancer cells." (PMID 40625712, 2023). "We further analyzed the difference in RNA expression of SIRT4 in 492 prostate cancers and 52 normal prostate tissues through the GEPIA website." (PMID 35842463, 2022). "We constructed stable strains with SIRT4 overexpression and suppression of 22RV1 prostate cancer cells via lentiviral infection and confirmed the results by RT-PCR and Western Blotting." (PMID 35842463, 2022). "In this study, we evaluated the associations between immunohistochemical SIRT4 protein expression in prostate cancer tissue and Gleason score to determine the clinical importance of SIRT4 expression in patients with prostate cancer." (PMID 35842463, 2022). "Further, shSIRT4 or stable prostate cancer cell lines (22RV1) overexpressing SIRT4 were constructed via lentiviral infection." (PMID 35842463, 2022). "Nevertheless, a study found that SIRT4 suppresses the proliferation of DU145 prostate cancer cells by inhibiting the uptake of glutamine, a metabolite vital for proliferating and cancerous cells." (PMID 36291902, 2022). "Notwithstanding, further studies are required to clarify the expression pattern of SIRT4 and its mechanistic roles in prostate cancer." (PMID 36291902, 2022). "SIRT4 suppressed the migration, invasion capabilities, and proliferation of prostate cancer cells and induced cellular apoptosis." (PMID 35842463, 2022). "Next, we explored the effects of SIRT4 on the proliferation of prostate cancer cells by inhibiting cell apoptosis." (PMID 35842463, 2022). "Using Cell-Counting Kit-8 (CCK-8) assay, wound healing assay, migration, and invasion and apoptosis assays, the effects of SIRT4 on the migration, invasion ability, and proliferation of prostate cancer cells were investigated." (PMID 35842463, 2022). "The results were consistent with our immunohistochemical findings that SIRT4 RNA levels were lower in prostate cancers than in normal prostate tissues." (PMID 35842463, 2022). "Li and colleagues found that, based on IHC analyses, SIRT4 expression in prostate-cancer tissues was significantly lower than that in matched paracancerous tissues, and that expression of SIRT4 protein was low in 9/12 frozen prostate-cancer tissues." (PMID 33585187, 2020).
prostate carcinoma (continued). "At the same time, in support of these present discoveries, it was also found that PAK6 and ANT2 are highly expressed, and that SIRT4 is lowly expressed in 9/12 frozen clinical prostate cancer tissues." (PMID 32194820, 2020). "In addition, the PAK6-SIRT4-ANT2 complex inhibited apoptosis in prostate cancer cells, and SIRT4 deprived ANT2 acetylation at the K105 site and promoted ubiquitinated degradation of ANT2." (PMID 39479446, 2024). "In contrast, further studies indicated that SIRT4 could inhibit the proliferation, migration, and invasive ability of prostate cancer cells by inhibiting glutamine metabolism." (PMID 40625712, 2023). "Additionally, in urological tumors, we recently reported that SIRT4 is critical for prostate cancer." (PMID 37301821, 2023). "In our in vitro study, by overexpressing and inhibiting SIRT4 gene in prostate cancer cells, we demonstrated that SIRT4 could significantly inhibit cell proliferation, migration, invasion capabilities, and cell cycle of prostate cancer cells." (PMID 35842463, 2022). "Finally, we investigated the effect of SIRT4 on L-Glutamine metabolism and its role in inhibiting the function of prostate cancer cells." (PMID 35842463, 2022). "Moreover, we investigated the in vitro effects of SIRT4 on prostate cancer cell proliferation, migration, invasion, cell cycle, and prostate cancer cell apoptosis by inhibiting and overexpressing the SIRT4 gene in 22RV1 cells." (PMID 35842463, 2022). "Next, we examined the effect of SIRT4 on the cell cycle of prostate cancer cells 22RV1." (PMID 35842463, 2022). "In this study, we evaluated SIRT4 protein levels in cancerous prostate tissue and corresponding non-tumor prostate tissue via immunohistochemical staining on a tissue microarray including tissues from 89 prostate cancer patients." (PMID 35842463, 2022). "To determine whether SIRT4 inhibits the invasion and migration of prostate carcinoma cells by inhibiting glutamine metabolism, we treated 22RV1 cells with DM-αKG." (PMID 35842463, 2022). "To date, the clinical impact of SIRT4 on prostate cancer has yet to be defined." (PMID 32194820, 2020). "Therefore, it was considered that the degradation of ANT2 by SIRT4 would provide a new target for the treatment of prostate cancer." (PMID 32194820, 2020). "Hence, the association of SIRT4 and ANT2 was verified by immunoprecipitation in prostate cancer cells." (PMID 32194820, 2020). "Moreover, glucose uptake was unaffected by SIRT4 expression in prostate cancer studies." (PMID 40625712, 2023). "However, there are few studies about the effects of SIRT4 on prostate cancer cells." (PMID 35842463, 2022). "However, the relationship between SIRT4 and prostate cancer remains to be elucidated." (PMID 35842463, 2022). "However, few is known about the roles of SIRT4 in prostate cancer." (PMID 32194820, 2020). "In prostate cancer cells, ANT2 was found to be deacetylated by SIRT4 at lysine 105, which promoted ubiquitin‐mediated ANT2 degradation." (PMID 40288905, 2025). "In this study, we show that the mitochondrial Sirtuin 4 (SIRT4), which has ADP-ribosylation activity, plays a role in prostate cancer (PCa) progression." (PMID 35847357, 2022). "Thus, SIRT4 may serve as a potential novel therapeutic target for prostate cancer." (PMID 35842463, 2022). "However, the clinical significance of SIRT4 in prostate cancer remains unknown." (PMID 35842463, 2022). "Consistently, these clinical prostate cancer tissue evaluations reveal that PAK6 is positively correlated with ANT2 expression, but negatively correlated with SIRT4." (PMID 32194820, 2020). "We found the protein levels of SIRT4 in prostate cancer tissues were significantly lower than those in their non-neoplastic tissue counterparts (P < 0.01); a lower SIRT4 level was also significantly associated with a higher Gleason score (P < 0.01)." (PMID 35842463, 2022).
prostate carcinoma (continued). "In this study, using immunohistochemical analysis, we revealed that the expression of SIRT4 in prostate cancer tissues was significantly lower than that in adjacent non-neoplastic prostate tissues." (PMID 35842463, 2022). "A significant negative correlation was observed between SIRT4 expression and the Gleason score in prostate cancer in the present study." (PMID 35842463, 2022). "SIRT4 is downregulated on immunohistochemical staining of human prostate cancer and adjacent non-neoplastic tissues." (PMID 35842463, 2022). "Dramatically, it was found that prostate cancer tissues had apparently higher PAK6 and ANT2 expression, but had dramatically lower SIRT4 expression, when compared to paired adjacent non-neoplastic tissues." (PMID 32194820, 2020).
Obesity (10 papers, 2014 to 2022). Accumulation of substantial excess body fat. "Moreover, SIRT4 KO mice showed increased fatty acid oxidation in various tissues such as the liver and myotubes, and were protected from obesity caused by high-fat diet, while remaining insulin resistant." (PMID 30442871, 2018). "SIRT4 stimulates lipoge-nesis in the white adipose tissue, whereas SIRT4 knockout mice are protected against diet-induced obesity and show an increased exercise capacity." (PMID 33806509, 2021). "This regulatory mechanism was confirmed in Sirt4 knock-out (KO) mice that showed raised FAO associated with increased exercise tolerance and resistance to diet-induced obesity." (PMID 32373514, 2020). "Previous studies have reported that SIRT4 affects important biological pathways, especially those involved in metabolic diseases such as diabetes, obesity, and cancer." (PMID 30442871, 2018). "Moreover, the drug T1AM increases SIRT6 levels, whereas it decreases SIRT4 levels, as well as reversing obesity through metabolic reprogramming." (PMID 33806509, 2021). "Also, circulating levels of SIRT4 has been explored as a potential biomarker of oxidative metabolism for CAD in patients with obesity." (PMID 31447696, 2019). "It has been reported that the lipid metabolism of SIRT4 KO mice was deregulated, leading to a metabolic shift toward lipid utilisation, thus enhancing exercise tolerance and protecting against diet-induced obesity." (PMID 31447696, 2019). "Finally, we found that circulating levels of Sirt4 were negatively correlated with surrogate markers of ectopic fat storage and visceral fat dysfunction, independently of the severity of the obesity." (PMID 28706576, 2017). "In other words, obese individuals with moderately low SIRT4 levels, due to disturbed muscle fat β-oxidation—a primary event in the etiology of obesity—were still able to provide a sufficient β-oxidation of FFAs that leads to less organ fat storage without forming excess ROS." (PMID 25045415, 2014). "Recently, it has been reported that SIRT4 KO mice can run 20% more distance and longer time than wild-type mice facing a graded, maximal treadmill challenge, which may be related to increased fatty acid oxidation, enhanced exercise capacity and resistance to diet-induced obesity." (PMID 31447696, 2019). "Serum levels of SIRT4 were not significantly different between the three degrees of obesity (ANOVA Kruskal-Wallis, P = 0.9)." (PMID 25045415, 2014). "It has been reported that, in SIRT4 knocked-out (KO) mice, the MCD activity was increased and the level of malonyl CoA was decreased in skeletal muscle and white adipose tissue, leading to elevated exercise tolerance, which was considered to have a protective effect on diet-related obesity." (PMID 31447696, 2019). "The novel finding of this study was that lower serum levels of SIRT4 were present in obese subjects with HS and IMTG, independent of the severity of obesity." (PMID 25045415, 2014). "When deacetylated by SIRT4, MCD functions less efficiently, and animals lacking SIRT4 present with increased MCD activity, dysregulated lipid metabolism, and protection against diet-induced obesity." (PMID 25332769, 2014).
Sepsis (10 papers, 2018 to 2026). Sepsis is defined as life-threatening organ dysfunction caused by a dysregulated host response to infection. "The most crucial contribution of this study lies in the precise mechanism‐association between Sirt4 and mitochondrial quality control in sepsis." (PMID 41523985, 2026). "Sirtuin 4 (Sirt4) plays a regulatory role in mitochondrial function and metabolism, but its mechanism in liver injury caused by sepsis remains unclear." (PMID 41523985, 2026). "In conclusion, this study not only established the indispensable role of Sirt4 in ALI caused by sepsis but also revealed a protective mechanism by suppressing mitophagy, which induced by unbalanced mitochondrial dynamics including increased mitochondrial fission and decreased mitochondrial fusion." (PMID 41523985, 2026). "Sirt4 KO mice exhibited higher levels of serum AST/ALT, more severe liver tissue structure damage, and higher serum concentrations of proinflammatory factor IL‐6 after CLP surgery, which demonstrates that endogenous Sirt4 is an important molecular barrier against liver injury caused by sepsis." (PMID 41523985, 2026). "The main findings of this study are as follows: Firstly, we confirmed that in the CLP–induced sepsis model, the expression of Sirt4 in mouse liver was depressed." (PMID 41523985, 2026). "Our findings delineate a novel Sirt4‐DRP1–mitophagy axis as a critical regulatory mechanism in sepsis‐induced liver injury, suggesting Sirt4 as a potential therapeutic target." (PMID 41523985, 2026). "This discovery establishes a brand‐new protective role of Sirt4 in liver injury caused by sepsis, providing a new perspective for understanding the mechanism of organ damage in sepsis and positioning Sirt4 as a potential therapeutic intervention target." (PMID 41523985, 2026). "To figure out the role of Sirt4 in sepsis‐induced liver injury, we generated global Sirt4‐KO mice and subjected them to CLP." (PMID 41523985, 2026). "To determine the expression of Sirt4 in the livers of CLP–treated mice, we established a sepsis‐associated acute liver injury (ALI) model by CLP." (PMID 41523985, 2026). "Based on the mitochondrial localization of Sirt4 and its emerging role in the stress response, we propose a scientific hypothesis that Sirt4 may play an important protective role in liver injury caused by sepsis by regulating mitochondrial autophagy and kinetic balance." (PMID 41523985, 2026). "Previous studies on Sirt4 have mostly focused on the metabolic field, while this study extends its functional significance to the extreme stress state of sepsis." (PMID 41523985, 2026). "Sirt4 knockout (KO) aggravates liver injury in sepsis through increasing mitochondrial fission and mitophagy, which indicates a promising direction for future clinical treatment." (PMID 41523985, 2026). "Thirdly, Sirt4 regulated mitophagy via suppressing mitochondrial fission induced by sepsis in hepatocyte." (PMID 41523985, 2026). "Inhibition of miR-15b-5p upregulated SIRT4 content, alleviated sepsis-related inflammatory pathways, attenuated mitochondrial stress, and prevented apoptosis, pyroptosis, and autophagic mechanisms." (PMID 37587410, 2023). "Overall, these results demonstrate that i-PCSK9 protected endothelium in sepsis via SIRT4, indicating this epigenetic modulator as a possible innovative target against endothelial dysfunction induced by sepsis." (PMID 37587410, 2023). "Of note, SIRT4 emerges as a physiological player leading to hypo-inflammation and promoting sepsis recovery." (PMID 37587410, 2023). "Our in vitro findings suggested the miR-15b-5p–SIRT4 axis as a suitable target for LPS-induced inflammatory pathways occurring in sepsis, and provide additional knowledge on the beneficial effect of i-PCSK9 in preventing vascular damage by targeting SIRT4." (PMID 37587410, 2023).
Sepsis (continued). "Emerging evidence supports the role of sirtuins (SIRT1-7) in the progression and prognosis of sepsis acting on epigenetic profile, even if the involvement of SIRT4 in endothelial septic disorder is widely debated." (PMID 37587410, 2023). "Here, we provide the in vitro miR-15b-5p implication in the EC inflammatory response during sepsis and the possible relationship with SIRT4." (PMID 37587410, 2023). "Evidence suggests that expressed very late during hypo-inflammation, SIRT4 is a physiological mechanism that counters hypo-inflammation and is involved in sepsis resolution." (PMID 30216989, 2018). "SIRT4 expression increases in monocytes in vitro and in human sepsis blood monocytes that have been reprogrammed from hyper-inflammation to hypo-inflammation and endotoxin tolerance." (PMID 30216989, 2018). "However, the role of Sirt4 in sepsis, a major stress model, especially its function in the liver, a key organ, has been poorly studied." (PMID 41523985, 2026). "This discovery not only establishes the crucial position of Sirt4 in liver protection during sepsis, but more importantly, it directly links Sirt4 to the core pathological process of mitochondrial quality control, providing a promising perspective for clinical treatment of septic liver injury." (PMID 41523985, 2026). "Moreover, miR-15b-5p plays a detrimental role in sepsis by inhibiting SIRT4, thereby contributing to inflammation, oxidative stress, and endothelial dysfunction." (PMID 40407536, 2025). "In sepsis, the miR-15b-5p–SIRT4 axis may be a target for LPS-induced inflammatory pathways, whereas i-PCSK9 guards against vascular injury." (PMID 41567643, 2025). "In LPS-stimulated macrophages, overexpression of SIRT3 through SDHA deacetylation, mitigates sepsis-associated aerobic glycolysis.The role of SIRT4 in inflammatory immune responses is not entirely clear yet." (PMID 38690282, 2024). "Finally, i-PCSK9 enhanced the ability of i-miR-15b to restore the SIRT4 protein levels (p < 0.05 versus i-miR-15b + LPS), indicating the pivotal role of the miR-15b-5p–SIRT4 axis in endothelial dysfunction under sepsis." (PMID 37587410, 2023). "The role of SIRT4 in inflammation and sepsis is largely unexplored." (PMID 30216989, 2018). "Thus, SIRT4 seems to be a candidate for physiologically breaking in vitro endotoxin tolerance seen during sepsis; the in vivo role in sepsis needs further elucidation." (PMID 30216989, 2018). "Therefore, for macrophages, SIRT4 may be a counteracting factor against their anti-inflammatory response, concluding the endotoxin tolerance phase of sepsis." (PMID 38690282, 2024). "Therefore, HSP60 may serve as a target of SIRT4 in hepatocytes, improving ATP production and protecting from burn-sepsis-dependent organ injury." (PMID 38791521, 2024). "Besides, by regulating inflammation and metabolism shifts, SIRT4 may also participate in the development of sepsis." (PMID 30533222, 2018). "In this study, a sepsis mouse model was established through cecal ligation and puncture (CLP) surgery, and the liver injury phenotypes of wild‐type (WT; C57) mice and Sirt4 gene knockout (Sirt4-/- KO) mice were compared." (PMID 41523985, 2026). "We found that during sepsis, the elevated miR-15b-5p levels were related to vascular endothelial cell damage, robust inflammation, activation of the NLRP3 pathway, increased PCSK9 levels, and downregulation of SIRT4." (PMID 37587410, 2023).